TBCK (TBC1 domain containing kinase)
Description:
Component of the FERRY complex (Five-subunit Endosomal Rab5 and RNA/ribosome intermediary). The FERRY complex directly interacts with mRNAs and RAB5A, and functions as a RAB5A effector involved in the localization and the distribution of specific mRNAs most likely by mediating their endosomal transport. The complex recruits mRNAs and ribosomes to early endosomes through direct mRNA-interaction. Also involved in the modulation of mTOR signaling and expression of mTOR complex components. Involved in the control of actin-cytoskeleton organization.
Synonyms: Fy-1; FERRY1; TBCKL; HSPC302; MGC16169; IHPRF3
Tractability: PROTAC: it is named in the literature on targeted protein degradation; ubiquitination databases record sites on it; its protein half-life has been measured.
Gene: Protein-coding gene on chromosome 4 (106,041,599 to 106,316,683, reverse strand). Ensembl gene ENSG00000145348.
Subcellular location: Cytoplasm; Cytoplasm, cytoskeleton, spindle; Midbody; Early endosome
Subcellular location (Human Protein Atlas): Nucleoli fibrillar center; Nucleoplasm
Gene Ontology:
Molecular function: protein binding; ATP binding; GTPase activator activity; protein kinase activity
Biological process: actin cytoskeleton organization; cell population proliferation; regulation of TOR signaling; protein phosphorylation; regulation of intracellular mRNA localization
Cellular component: cytoplasm; midbody; mitotic spindle; early endosome; spindle
Genetic constraint (gnomAD): Loss-of-function variants: 48 observed, 57.48 expected, observed/expected ratio (o/e) 0.84, 90% interval 0.66 to 1.06. The upper end of that interval is the gene's LOEUF score, 1.06, which puts it in group 4 of 6, group 1 being the genes least tolerant of losing a copy. Missense variants: 667 observed, 703.2 expected, observed/expected ratio (o/e) 0.95, 90% interval 0.89 to 1.01. Synonymous variants: 265 observed, 249.36 expected, observed/expected ratio (o/e) 1.06, 90% interval 0.96 to 1.18.
Gene-disease validity (ClinGen):
ClinGen rates the evidence that TBCK causes each of these diseases.
syndromic complex neurodevelopmental disorder (autosomal recessive): Definitive. A disorder that involves more than one phenotype associated with the central nervous system, including but not limited to intellectual disability, autism, and seizures (epilepsy), and also a distinctive pattern of other features including dysmorphisms and/or congenital malformations.
Homologues: Orthologues: chimpanzee TBCK (99% identical), macaque TBCK (98% identical), dog TBCK (97% identical), pig TBCK (97% identical), rabbit TBCK (97% identical), mouse Tbck (95% identical), guinea pig TBCK (94% identical), rat Tbck (94% identical), tropical clawed frog tbck (81% identical), zebrafish tbck (76% identical), Drosophila melanogaster CG4041 (42% identical), Caenorhabditis elegans tbck-1 (27% identical). Paralogues in human: TBC1D9 (17% identical), TBC1D9B (17% identical), TBC1D8B (15% identical), RABGAP1 (15% identical), TBC1D4 (14% identical), TBC1D8 (14% identical), RABGAP1L (14% identical), TBC1D1 (14% identical), TBC1D2 (14% identical), TBC1D12 (13% identical), TBC1D10B (13% identical), TBC1D2B (12% identical), and 33 more.
Diseases named in the same sentence as TBCK in open-access papers:
TBCK is named in the same sentence as 36 diseases in open-access papers, as found by Europe PMC text mining. Sharing a sentence is not in itself a finding about the gene and the disease. The quoted sentences say what the papers report.
epilepsy (5 papers, 2018 to 2023). A brain disorder characterized by episodes of abnormally increased neuronal discharge resulting in transient episodes of sensory or motor neurological dysfunction, or psychic dysfunction. "Homozygous mutation of TBC1 domain-containing kinase (TBCK) is the cause of a very recently defined severe childhood disorder, which is characterized by severe hypotonia, global developmental delay, intellectual disability, epilepsy, characteristic facies and premature death." (PMID 30591081, 2018). "The TBCK syndrome is another very rare neurogenetic disorder that involves mutant TBC1 domain containing kinase (TBCK) gene (an activator of the mTOR signaling) and presents clinically as leukoencephalopathy, coarse face, neuropathy, epilepsy, hypotonia and intellectual disability." (PMID 36675042, 2023).
developmental delay (3 papers, 2018 to 2025). "Mutation of TBCK is associated with global developmental delay, hypotonia, and seizures." (PMID 40062705, 2025). "In 2015, a study seeking to identify the causative gene mutations in a large cohort of 143 families with neurological disorders identified both TBCK and FERRY3 as putative novel disease genes, with FERRY3 mutation associated with global developmental delay." (PMID 40062705, 2025).
Intellectual disability (3 papers, 2018 to 2025). "Mutation of TBCK causes TBCK syndrome, mutation of PPP1R21 is associated with PPP1R21-related intellectual disability, and mutation of FERRY3 results in an autosomal recessive intellectual disability." (PMID 40062705, 2025).
renal carcinoma (3 papers, 2019 to 2025). A carcinoma arising from the epithelium of the renal parenchyma or the renal pelvis. "TBCK knockdown via shRNA in a renal cancer cell line results in decreased mTORC2 signaling, as evidenced by decreased pAKT." (PMID 40062705, 2025). "Finally, we have established the possibility that TBCK has anti-apoptotic activity as demonstrated by the si-RNA-mediated knockdown of TBCK in renal cancer cells." (PMID 31331056, 2019). "Subsequently, we examined whether miR-1208 could directly bind to the 3′-UTR of TBCK in renal cancer cells." (PMID 31331056, 2019). "Furthermore, Kim et al25 reported that miR‐1208 could enhance cisplatin sensitivity by targeting TBCK in renal cancer cells, which indicates that miR‐1208 may be a tumour suppressor gene." (PMID 33320435, 2021). "In conclusion, the present study showed that TBCK was a direct target of miR-1208, and that miR-1208/TBCK interaction has an important role in the regulation of apoptosis as well as in the enhancement of cisplatin or TRAIL sensitivities in renal cancer cells." (PMID 31331056, 2019).
autism (2 papers, 2019 to 2021). Persistent deficits in social interaction and communication and interaction as well as a markedly restricted repertoire of activity and interest as well as repetitive patterns of behavior. "In this study, we described two new IHPRF3-affected sibs that present autism as an additional clinical feature of the syndrome and are compound heterozygotes for loss-of-function variants in TBCK." (PMID 35095425, 2021).
apical periodontitis (1 paper, 2025). "The most credible 3-UTR candidate variants were found in TBCK (rs79409042, chromosome 4) in the phenotype Necrosis of pulp or apical periodontitis, in HNRNPK (rs696825, chromosome 9) in Pulpal and apical diseases, and in MTMR3 (rs9983, chromosome 22) in Pulpitis." (PMID 40701953, 2025).
autism spectrum disorder (1 paper, 2018). A spectrum of developmental disorders that includes autism, and Asperger syndrome. "To date, few neurodevelopmental disorders have been linked to an aberrantly reduced mTOR signaling as seen in the herein described TBCK-DD, including Rett syndrome, Phelan-McDermid syndrome with autism spectrum disorder and Galloway-Mowat syndrome." (PMID 30591081, 2018).
colorectal adenocarcinoma (1 paper, 2013). The most common type of colorectal carcinoma. "A genome-wide screening project for cancer mutation has found that there are one missense mutation and one frameshift deletion of TBCK in colorectal adenocarcinoma and one missense mutation in head and neck squamous cell carcinoma." (PMID 23977024, 2013).
kidney cancer (1 paper, 2019). Primary or metastatic malignant neoplasm involving the kidney. "Moreover, miR-1208 directly targets TBCK by interacting with two binding sites in the 3′-UTR, which is involved in miR-1208-induced apoptosis and, in turn, increases susceptibility to cisplatin or TRAIL in kidney cancer cells." (PMID 31331056, 2019).
lysosomal storage disease (1 paper, 2018). A metabolic disorder caused by mutations in proteins critical for lysosomal function, including lysosomal enzymes, lysosomal integral membrane proteins, and proteins involved in the post-translational modification and trafficking of lysosomal proteins. "These investigations strikingly uncover TBCK-DD as a novel type of lysosomal storage disease which is characterized by different storage products rather than one specific type of accumulated material." (PMID 30591081, 2018).
myoclonic epilepsy (1 paper, 2025). A group of epilepsy syndromes in which myoclonic seizures are a prominent feature. "The individual carrying the benign T1250M variant had myoclonic epilepsy, attributed to a pathogenic TBCK variant identified after SCN1A testing." (PMID 39838578, 2025).
virus infection (1 paper, 2013). "Western blotting showed that the protein level of TBCK was decreased in cells infected with either TBCK-RNAi-1 or TBCK-RNAi-2 compared with that of control virus infection (RNAi-con)." (PMID 23977024, 2013).
tumor (7 papers, 2017 to 2025). "In patients with hepatocellular carcinoma, sequencing of circular tumor DNA revealed the presence of frameshift-inducing insertional mutations in TBCK." (PMID 40062705, 2025). "In addition, depending on the cell type, TBCK has been associated with both tumor-promoting and tumor-suppressive function, suggesting variable regulation according to the cell type." (PMID 35095425, 2021). "Therefore, it is necessary to identify the upstream regulators of TBCK that function in the suppression of tumor growth and enhancement of drug susceptibility." (PMID 31331056, 2019). "We observed a higher mRNA expression of TBC1D10C, TBC1D4, TBC1D12, TBCK, TBC1D5, TBC1D30 and a lower expression of TBC1D24 in patients with tumor compared with tumor free patients." (PMID 33194704, 2020).
neurologic disorders (1 paper, 2025). "Here, we have described three rare neurologic disorders resulting from mutations in either TBCK, PPP1R21, or FERRY3." (PMID 40062705, 2025). "Mutations in TBCK were first associated with a neurological disorder in 2015." (PMID 40062705, 2025). "Notably, mutations in three different members of the FERRY complex (TBCK, PPP1R21, and FERRY3) are associated with rare neurologic disorders in human patients." (PMID 40062705, 2025).
TBCK also shares sentences with these, for which no sentence is quoted: cancer (4 papers); neurodevelopmental disorder (2); Alzheimer disease (1); Cognitive impairment (1); cortical atrophy (1); Escobar syndrome (1); Galloway-Mowat syndrome (1); genetic disorder (1); head and neck squamous cell carcinoma (1); hepatocellular carcinoma (1); Leukoencephalopathy (1); microcephaly (1); neuromuscular disease (1); neuronal ceroid lipofuscinosis (1); neuropathy (1); Phelan-McDermid syndrome (1); pontocerebellar hypoplasia, type 1C (1); prostate carcinoma (1); pulpitis (1); Rett syndrome (1); skin cutaneous melanoma (1); spondylometaphyseal dysplasia (1).